MARCHF5 (membrane associated ring-CH-type finger 5)
Description:
Mitochondrial E3 ubiquitin-protein ligase that plays a crucial role in the control of mitochondrial morphology by acting as a positive regulator of mitochondrial fission and as an important regulator of immune response. Plays a crucial role in maintaining mitochondrial homeostasis by regulating the dynamics of mitochondria through the ubiquitination of key proteins involved in fission and fusion such as FIS1, DNM1L and MFN1. Acts as a critical determinant of mitotic apoptosis through both MCL1-dependent and -independent pathways (By similarity). Turns off persistent immune signaling by degrading oligomeric complexes of retinoic acid-inducible gene I/DDX58 and mitochondrial antiviral-signaling protein/MAVS formed upon RNA virus infection. Promotes STING-mediated type-I interferon production via 'Lys-63'-linked ubiquitination of STING1 thereby preserving its activity and preventing the formation of inactive STING1 polymers. Plays also an essential role in the formation of PEX3-containing vesicles in the de novo biogenesis of peroxisomes from mitochondria. Acts as a regulator of NLRP3 inflammasome activation on the mitochondria by mediating the 'Lys-27'-linked polyubiquitination of NLRP3, positively regulating the NLRP3-NEK7 complex formation and NLRP3 oligomerization. (Microbial infection) Plays a positive role in Japanese encephalitis virus infection by catalyzing the 'Lys-27'-linked polyubiquitination of viral E protein to facilitate efficient viral attachment.
Synonyms: MARCH-V; MITOL; MARCH5; RNF153; FLJ20445
Tractability: Antibody: UniProt predicts a signal peptide or a membrane-spanning region. PROTAC: UniProt records ubiquitination sites on it; ubiquitination databases record sites on it.
Gene: Protein-coding gene on chromosome 10 (92,291,167 to 92,353,964, forward strand). Ensembl gene ENSG00000198060.
Subcellular location: Mitochondrion outer membrane; Endoplasmic reticulum membrane; Peroxisome membrane
Subcellular location (Human Protein Atlas): Mitochondria
Gene Ontology:
Molecular function: GTPase binding; protein binding; ubiquitin protein ligase activity; zinc ion binding
Biological process: negative regulation of cytoplasmic pattern recognition receptor signaling pathway; positive regulation of cGAS/STING signaling pathway; positive regulation of mitochondrial fission; positive regulation of NLRP3 inflammasome complex assembly; protein autoubiquitination; protein K27-linked ubiquitination; protein K48-linked ubiquitination; protein K63-linked ubiquitination; protein localization to mitochondrion; protein polyubiquitination; regulation of mitochondrial fission; protein ubiquitination
Cellular component: endoplasmic reticulum; endoplasmic reticulum membrane; membrane; mitochondrial outer membrane; mitochondrion; peroxisomal membrane
Genetic constraint (gnomAD): Loss-of-function variants: 5 observed, 26.72 expected, observed/expected ratio (o/e) 0.19, 90% interval 0.097 to 0.39. The upper end of that interval is the gene's LOEUF score, 0.39, which puts it in group 1 of 6, group 1 being the genes least tolerant of losing a copy. Missense variants: 144 observed, 294.92 expected, observed/expected ratio (o/e) 0.49, 90% interval 0.43 to 0.56. Synonymous variants: 84 observed, 94.71 expected, observed/expected ratio (o/e) 0.89, 90% interval 0.74 to 1.06.
Homologues: Orthologues: chimpanzee MARCHF5 (100% identical), dog MARCHF5 (100% identical), guinea pig MARCHF5 (100% identical), macaque MARCHF5 (100% identical), mouse Marchf5 (100% identical), rabbit MARCHF5 (100% identical), rat Marchf5 (100% identical), zebrafish marchf5 (96% identical), tropical clawed frog marchf5 (95% identical), pig MARCHF5 (73% identical), Drosophila melanogaster CG9855 (54% identical), Drosophila melanogaster CG16781 (45% identical), and 3 more.
Diseases named in the same sentence as MARCHF5 in open-access papers:
MARCHF5 is named in the same sentence as 64 diseases in open-access papers, as found by Europe PMC text mining. Sharing a sentence is not in itself a finding about the gene and the disease. The quoted sentences say what the papers report.
tumor (15 papers, 2016 to 2025). "Mechanistically, we find that MARCHF5 induces the turnover of NOXA protein thereby reinforcing the pro-survival role of MCL1 in these tumor cells." (PMID 39386614, 2024). "We propose that MARCHF5 induces the degradation of the MCL1 antagonist NOXA thus reinforcing the pro-survival role of MCL1 in these tumor cells." (PMID 39386614, 2024). "It is possible that the addiction to MARCHF5 also involves the regulation of mitochondrial dynamics to meet the altered energy demands of these actively proliferating tumor cells." (PMID 39386614, 2024).
MARCHF5 also shares sentences with these, for which no sentence is quoted: cancer (25 papers); ovarian carcinoma (10); breast carcinoma (9); viral infection (8); melanoma (5); colorectal cancer (4); hepatocellular carcinoma (4); infection (4); myocardial infarction (4); neurodegenerative disease (4); Alzheimer disease (3); amyotrophic lateral sclerosis (3); cardiovascular disease (3); heart disease (3); heart failure (3); liver cancer (3); acute myeloid leukaemia (2); cardiac hypertrophy (2); cardiac ischemia (2); diabetic cardiomyopathy (2); glaucoma (2); lymphoma (2); neuroblastoma (2); prostate carcinoma (2); Sepsis (2); systemic lupus erythematosus (2); amyloidosis (1); bacterial infection (1); bladder cancer (1); breast (1).
A further 33 diseases each share a sentence with MARCHF5 in 1 paper.